MIR4776-2 (microRNA 4776-2)
Synonyms: hsa-mir-4776-2; mir-4776-2
Gene: MicroRNA gene on chromosome 2 (212,926,257 to 212,926,336, reverse strand). Ensembl gene ENSG00000283637.
Homologues: Orthologues: chimpanzee MIR4776-2 (100% identical).